COL4A2 (collagen type IV alpha 2 chain)
Diseases named in the same sentence as COL4A2 in open-access papers (continued):
Sharing a sentence is not in itself a finding about the gene and the disease.
porencephaly (10 papers, 2014 to 2025). Porencephaly is characterized by a circumscribed intracerebral cavity of variable size that may be bordered by abnormal polymicrogyric gray matter. "A case study of a patient with porencephaly (cystic brain lesions) carrying a collagen IV α2 mutation, which caused intracellular accumulation of the COL4A2 chain, found ER stress and UPR activation, which could be rescued by chemical chaperone treatment." (PMID 37837732, 2023). "Here, we identify a novel COL4A2 mutation in a pedigree with porencephaly." (PMID 24001601, 2014). "Large scale studies validated COL4A1 mutations as frequent causes of porencephaly and schizencephaly and COL4A1 and COL4A2 as frequent causes of prenatal hemorrhagic or ischemic cerebral lesions." (PMID 41311701, 2025). "Other types of porencephaly show a similar spectrum, but are caused by mutations of COL4A1 or segment deletions of chromosome 13, which affect both the COL4A2 and COL4A1 genes." (PMID 31331924, 2019). "Although epilepsy is recognized as a clinical manifestation of porencephaly, the specific mechanism of Col4a2-related epileptic phenotypes remains unclear." (PMID 39006838, 2024). "Compared to disease caused by variants in the coding regions of COL4A1 and COL4A2, PADMAL has a later age at onset and does not lead to cerebral hemorrhages, or porencephaly." (PMID 36786861, 2023).
cerebral small vessel disease (9 papers, 2016 to 2024). Cerebral small vessel disease is the term currently used to pathological processes that affect the brain parenchymal circulation (arterioles, capillaries, and veins). "The association with COL4A2 (rs9515201) is in strong LD (r2 > 0.8) with SNPs previously reported to be associated with cerebral small vessel disease, and is therefore likely to represent the same locus." (PMID 26674333, 2016). "Disruption of the vascular ECM has been hypothesised to be a key component in pathogenesis of cerebral small vessel disease, particularly in monogenic forms, and several of the genes implicated in this study (COL4A2, LOX, SH3PXD2A, GPR126, HTRA1) have key roles in the ECM." (PMID 33773637, 2021). "Collagen isoforms COL4A1 and COL4A2, defined in a GWAS analysis of cerebral small vessel disease as mainly expressed in the brain endothelial cells." (PMID 35008650, 2021). "For patients carrying variants outside EGFr region, no potential pathogenic mutation were identified in several other genes known to be common causal of cerebral small-vessel disease or vascular dementia (HTRA1, TREX1, COL4A1, COL4A2, GLA, APP, and ITM2B) by targeted next-generation sequencing." (PMID 34335700, 2021).
cerebrovascular disease (7 papers, 2016 to 2023). "These genes encode major basement membrane collagen proteins COL4A1 and COL4A2, and their mutations cause cerebrovascular diseases." (PMID 37958635, 2023). "The COL4A1 and COL4A2 mutations were important causes of cerebrovascular disease with a high mutation detection rate in porencephaly and childhood cerebral hemorrhage, and a relatively high rate of de novo mutations." (PMID 31484286, 2019). "COL4A1 and COL4A2 mutations cause a multisystem disorder characterized by the presence of cerebrovascular disease with variable ocular, renal and muscular involvement." (PMID 29895609, 2018). "COL4A1, and COL4A2 are highly conserved across species and dominant-negative mutations in these genes are pleiotropic and contribute to a broad spectrum of disorders including myopathy, glaucoma, and cerebrovascular disease." (PMID 33918807, 2021). "COL4A1 and COL4A2 mutations have been reported in a broad spectrum of disorders, including myopathy, glaucoma, cerebrovascular disease, and renal, ophthalmological, cardiac, and muscular abnormalities, which were collectively termed “COL4A1 and COL4A2 mutation-related disorders”." (PMID 31484286, 2019). "The identification of rare mutations in sporadic haemorrhaging, and that common COL4A2 variants are a risk factor for deep ICH and white matter hyperintensities in the general population, underscore an important role for COL4A1/COL4A2 in common cerebrovascular disease and ICH." (PMID 30351356, 2019). "Despite a growing recognition for the roles of COL4A1 and COL4A2 mutations in the etiology of cerebrovascular disease and myopathy, there are currently no targeted therapeutic interventions." (PMID 29895609, 2018). "Here we show that, in addition to increased risk for cerebrovascular disease (and other multi-systemic complications), patients with COL4A1 or COL4A2 mutations should be carefully monitored for progressive retinal neovascularization that could lead to sudden blindness." (PMID 26813606, 2016). "We found that genes related to cerebrovascular diseases, such as COL4A1, COL4A2, VCAN and APOE were significantly enriched in the cerebrovascular ECM network." (PMID 33730931, 2021).
epilepsy (7 papers, 2018 to 2026). A brain disorder characterized by episodes of abnormally increased neuronal discharge resulting in transient episodes of sensory or motor neurological dysfunction, or psychic dysfunction. "To investigate the impact of the Col4a2 mutation on epilepsy, we choose an unreported mutation site Col4a2Mut (c.1838G>T) and introduced itinto the CTX-CNA astrocyte cell line and primary astrocytes." (PMID 39006838, 2024). "Our clinical data showed that proinflammatory cytokine levels are elevated in the cerebrospinal fluid of patients with Col4a2 mutation-associated epilepsy, whereas the levels of these proinflammatory cytokines can be reduced after effective treatment." (PMID 39006838, 2024). "Our study indicated that astrocyte activation and neuroinflammation are significant aspects of epilepsy associated with Col4a2 mutations." (PMID 39006838, 2024). "Our initial investigation into the role of the JAK/STAT pathway in the pathogenesis of Col4a2 mutation-associated epilepsy has laid a foundation for future research on therapeutic approaches." (PMID 39006838, 2024). "As neuroinflammation was identified in Col4a2 mutation-associated epilepsy, further investigation into the potential pathways activating the inflammatory response was necessary." (PMID 39006838, 2024). "In our study, we identified a child with epilepsy who carried the same Col4a2 mutation as his mother." (PMID 39006838, 2024). "Our study indicates that mutations in Col4a2 can trigger astrocyte activation and neuroinflammation in epilepsy through the JAK/STAT pathway." (PMID 39006838, 2024). "Then, we established an LPS-induced astrocyte model to evaluate the effects of the Col4a2 mutation on epilepsy progression." (PMID 39006838, 2024). "The C-terminal portion of COL4A2 arrests cell proliferation and migration; mutations in DD-candidate COL4A2 have been found in patients suffering from epilepsy and severe developmental delay." (PMID 30405489, 2018). "In our series of new and published patients, the neurologic patterns associated with COL4A1/COL4A2 mutations comprised a typical severe presentation and a spectrum of less common phenotypes, in which epilepsy can be the predominant feature." (PMID 30413629, 2018). "COL4A1/COL4A2 mutations typically cause a severe neurologic condition and a broader spectrum of milder phenotypes, in which epilepsy is the predominant feature." (PMID 30413629, 2018). "Epilepsy resulting from mutations in the Col4a2 gene is often caused by de novo mutations." (PMID 39006838, 2024). "Additionally, we conducted a preliminary investigation of the role of the JAK/STAT pathway in Col4a2 mutation-associated epilepsy." (PMID 39006838, 2024). "This pathway could serve as an effective target for new therapies in Col4a2 mutation-associated epilepsy." (PMID 39006838, 2024). "Interestingly, mutations in Col4a1 and Col4a2 can cause neuromuscular dysfunction, vascular defects, myopathies and neurological disorders including epilepsy and cortical malformations." (PMID 31615574, 2019). "Broadening the spectrum of clinical phenotypes associated with COL4A1/COL4A2 mutations may help our understanding of the genetic architecture of the epilepsies." (PMID 30413629, 2018). "Notably, neuroinflammation and astrocyte activation are vital features of epilepsy linked to Col4a2 mutations and may be regulated via the JAK/STAT signaling pathway." (PMID 39006838, 2024). "Furthermore, we aimed to investigate the role of Col4a2 mutations in the development of epilepsy." (PMID 39006838, 2024). "Additionally, our study revealed the presence of an inflammatory microenvironment in Col4a2 mutation-associated DEEs and suggested that this type of epilepsy may be associated with a type VII inflammatory microenvironment according to the functional classification of genes causing DEEs." (PMID 39006838, 2024).
epilepsy (continued). "We hypothesized that epilepsy could be a manifestation of disease even in patients in whom porencephaly is not evident and aimed to characterize the phenotypes associated with COL4A1/COL4A2 mutations, seeking genotype–phenotype correlation." (PMID 30413629, 2018). "The epilepsy phenotypes associated with COL4A1/COL4A2 mutations suggest that this may not be the most comprehensive strategy to determine the full effect of genetic variation in the causation and biology of the epilepsies, or to best apply genetically driven precision medicine approaches." (PMID 30413629, 2018).
glioma (7 papers, 2021 to 2026). A benign or malignant brain and spinal cord tumor that arises from glial cells (astrocytes, oligodendrocytes, ependymal cells). "We found the high expressions in COL4A1 and COL4A2 were positively related to a worse prognosis of glioma patient, while, in COL4A3 and COL4A4 were predicted to a better prognosis." (PMID 40351420, 2025). "The further analysis showed that COL4A1 and COL4A2 had similar upregulated expression levels in glioma tumor tissues." (PMID 40351420, 2025). "COL4A1, COL4A2 could regulate the immunosuppressive microenvironment of glioma." (PMID 40351420, 2025). "In TCGA, GEO (GSE50161, GES7696, GES4290) and CGGA (mRNAseq_325) databases, we found the COL4A1, COL4A2 and COL4A6 expression were significantly increased in glioma tissues." (PMID 40351420, 2025). "By comparing the expression level in different histological types of gliomas, COL4A1 and COL4A2 were better predictors of glioblastoma (AUC = 0.918 and 0.9), followed by COL4A3 and COL4A4 (AUC = 0.67 and 0.746)." (PMID 40351420, 2025). "Higher expression of COL1A1, COL1A2, COL3A1, COL4A1, COL4A2, and COL5A2 was negatively correlated with the prognosis of glioma patients." (PMID 38969910, 2024). "In detail, COL1A1, COL1A2, COL3A1, COL4A1, and COL4A2 positively correlated with the infiltration of B cells, CD8+T cells, CD4+T cells, macrophages, neutrophils, and dendritic cells in low-grade glioma." (PMID 38969910, 2024). "Then, six collagen genes (COL1A1, COL1A2, COL3A1, COL4A1, COL4A2, and COL5A2) were selected for further validation in Oncomine, TCGA (The Cancer Genome Atlas), and CGGA (Chinese Glioma Genome Atlas) database." (PMID 34034744, 2021). "On the CGGA website (mRNAseq_325), collagen genes (COL1A1, COL1A2, COL3A1, COL4A1, COL4A2, and COL5A2) in WHO grades II, III, and IV glioma samples were analyzed to explore the expression levels of these genes." (PMID 34034744, 2021). "In contrast, COL4A2 and SOX10 appear to act as tumor suppressors in glioma pathophysiology." (PMID 41727650, 2026). "In conclusion, the collagen genes (COL1A1, COL1A2, COL3A1, COL4A1, COL4A2, and COL5A2) could regulate the immunosuppressive microenvironment and be involved in the EMT process of glioma." (PMID 34034744, 2021). "Importantly, we identified that 6 collagen genes (COL1A1, COL1A2, COL3A1, COL4A1, COL4A2, and COL5A2) could regulate the immunosuppressive microenvironment of glioma." (PMID 34034744, 2021).
hepatocellular carcinoma (7 papers, 2021 to 2024). A malignant tumor that arises from hepatocytes. "Another CHD SNP enriched in the hepatitis C and hepatocellular carcinoma pathway is rs11838776*A (COL4A2: type IV collagen α2 chain), which is associated with 1.03 times (95% CI: 1.02–1.04) higher CHD risk in our meta-analysis." (PMID 36292250, 2022). "Likewise, other studies reported significantly upregulated expression of COL4A1 and COL4A2 in patients with liver cirrhosis and hepatocellular carcinoma." (PMID 36768808, 2023). "Co-treatment with KPA also decreased the expression of genes, regulating the progression of fibrosis (e.g., COL6A3, AEBP1, SPARC, TNC, LAMB1, BGN) and hepatocellular carcinoma (e.g., COL4A1, COL4A2, TUFT1, VCAN, NID1)." (PMID 39404414, 2024). "Previously, it has also been found that COL4A2 activates the RhoA/ROCK pathway to facilitate the growth and metastasis of hepatocellular carcinoma (HCC) cells." (PMID 34477476, 2021).
atherosclerosis (6 papers, 2017 to 2025). A disease characterized by the build-up of fatty material and calcium deposition in the arterial wall resulting in partial or complete occlusion of the arterial lumen. "COL4A2 rs9515203 has previously shown association with sub-clinical atherosclerosis, and coronary artery disease." (PMID 33171725, 2020). "Perhaps the effects of COL4A1/COL4A2 variation occur early in development of atherosclerosis, setting the stage for effects of other genetic variants in subsequent phases of atherogenesis." (PMID 28642624, 2017). "In atherosclerosis, ECs communicated extensively with pericyte cells and SMCs through LAMININ (LAMA5-(ITGA1+ITGB1), LAMA5-(ITGA7+ITGB1), LAMB2-(ITGA6+ITGB4), LAMB2-(ITGA6+ITGB1)) and COLLAGEN (COL4A1-(ITGA1+ITGB1), COL4A2-(ITGA1+ITGB1)) pathways." (PMID 40225569, 2025).
coronary artery disease (6 papers, 2016 to 2022). "These genes included Cdh13 and Lpl from Cluster 1; Nfia, Col4a1 and Serpinh1 from Cluster 2; Arhgef12, Col4a2, Scarb1 and Cst3 from Cluster 3; Pecam1 and Aldh2 from Cluster 4, providing plausible molecular basis for the inextricable causal link between age and coronary artery disease." (PMID 35615560, 2022). "Genome-wide association studies have revealed an association between coronary heart disease (CHD) and genetic variation on chromosome 13q34, with the lead single nucleotide polymorphism rs4773144 residing in the COL4A2 gene in this genomic region." (PMID 27389912, 2016). "In addition, our analyses suggested that genetic variations at the ANKS1A, COL4A2 and APOE loci previously found associated with coronary artery disease in the general population could have stronger effects in patients with type 1 diabetes." (PMID 29695241, 2018).
gastric cancer (5 papers, 2018 to 2025). A primary or metastatic malignant neoplasm involving the stomach. "Consistently, the protein level of COL4A1 was elevated, whereas the protein level of COL4A2 was reduced in the gastric cancer cell lines." (PMID 38907304, 2024). "However, gastric cancer cells exhibited downregulation of COL4A2." (PMID 38907304, 2024). "A previous study showed that seven collagen genes (COL1A2, COL4A1, COL6A2, COC6A1, COL4A2, and COL11A1) were highly expressed in gastric cancer tissues, consistent with our findings." (PMID 39220121, 2024).
glaucoma (5 papers, 2016 to 2024). Increased pressure in the eyeball due to obstruction of the outflow of aqueous humor. "Mutations in the genes encoding type IV collagen alpha 1 (COL4A1) and alpha 2 (COL4A2) cause a multisystem disorder that includes ocular anterior segment dysgenesis (ASD) and glaucoma." (PMID 38717426, 2024).
Gould syndrome (5 papers, 2022 to 2025). "Rare, dominant, coding mutations of COL4A1 and COL4A2 cause monogenic cerebrovascular disease as part of a highly variable multisystem disorder named Gould syndrome." (PMID 41311701, 2025). "Missense mutations in COL4A1/COL4A2 cause early-onset CSVD with ICH in COL4A1 (Gould) Syndrome, while rare missense variants and common non-coding variants have also emerged as risk factors." (PMID 39216230, 2024). "Accordingly, semi-dominant COL4A1 and COL4A2 mutations cause Gould syndrome characterized primary by cerebrovascular manifestation in which TGF-β signaling is overactivated." (PMID 38980840, 2024). "COL4A1 and COL4A2 mutations cause Gould syndrome, a multisystem disorder mainly associated with cerebrovascular, ocular, renal, and muscular defects with variable disease onset, penetrance, and severity." (PMID 38717426, 2024). "BM defects, collagen IV misfolding with ER retention and ER stress can occur due to COL4A1/COL4A2 mutations, 10, 11 but the molecular cross-talk and relative contribution of these upstream molecular insults to the pathologies in Gould syndrome remains unknown." (PMID 39216230, 2024). "Consistent with their ubiquitous expression pattern, mutations in COL4A1 and COL4A2 cause a clinically heterogenous multisystem disorder characterized by cerebrovascular, ocular, renal, and muscular manifestations that are collectively referred to as Gould syndrome." (PMID 38717426, 2024). "Murine models of Col4a1 and Col4a2 mutations faithfully replicate Gould syndrome and allelic heterogeneity was shown to modulate the severity of ICH in an allelic series of Col4a1 and Col4a2 mutant mice." (PMID 41311701, 2025). "Previously, we successfully demonstrated that Col4a1 and Col4a2 mutant mice can recapitulate pathophysiological hallmarks of Gould syndrome, including ICH, whose severity was modulated by allelic heterogeneity." (PMID 41311701, 2025). "This provides evidence that in late-onset sporadic CSVD coding variants do not affect collagen IV secretion, in contrast to COL4A1/COL4A2 mutations in early-onset familial Gould syndrome." (PMID 39216230, 2024). "Gould syndrome is a highly variable multisystem disorder caused by COL4A1 and COL4A2 mutations, whose clinical presentation can vary widely between and within families ranging from asymptomatic COL4A1/COL4A2 mutation carriers to severely disabled individuals (Guey and Hervé, 2022)." (PMID 41311701, 2025). "Furthermore, since perinatal cerebral hemorrhage is a cardinal feature of Gould syndrome, we performed a genetic screen for PLOD3 variants in a fetal stroke cohort that was negative for COL4A1 and COL4A2 pathogenic variants." (PMID 36403858, 2022).
intracranial hemorrhage (5 papers, 2018 to 2026). Bleeding within the SKULL, including hemorrhages in the brain and the three membranes of MENINGES. "Disruptions of the genes, such as the COL4A1 and COL4A2 genes, are common genetic causes identified in fetal intracranial hemorrhage; however, the disruptions of the JAM3 gene are rarely reported." (PMID 36339007, 2022). "Therefore, COL4A2 variants are associated with fetal and neonatal hemorrhages and spontaneous recurrent intracranial hemorrhages." (PMID 38790247, 2024). "The presence of cerebral microbleeds on brain MRI might help to identify those with COL4A1/COL4A2 mutations at highest risk of intracranial hemorrhage prior to anticoagulation or thrombolysis." (PMID 30413629, 2018).